NPTX1 (neuronal pentraxin 1)
Description:
May be involved in mediating uptake of synaptic material during synapse remodeling or in mediating the synaptic clustering of AMPA glutamate receptors at a subset of excitatory synapses.
Synonyms: NP1; SCA50
Tractability: Antibody: UniProt places it where antibodies can reach, with high confidence; UniProt predicts a signal peptide or a membrane-spanning region; its Gene Ontology location is reachable by antibodies, with medium confidence. PROTAC: ubiquitination databases record sites on it; its protein half-life has been measured.
Gene: Protein-coding gene on chromosome 17 (80,466,834 to 80,477,843, reverse strand). Ensembl gene ENSG00000171246.
Subcellular location: Secreted; Cytoplasmic vesicle, secretory vesicle; Endoplasmic reticulum
Subcellular location (Human Protein Atlas): Golgi apparatus; Vesicles; Predicted to be secreted
Gene Ontology:
Biological process: axonogenesis involved in innervation; central nervous system development; chemical synaptic transmission; cellular response to glucose stimulus; cellular response to potassium ion; mitochondrial fragmentation involved in apoptotic process; mitochondrial transport; neurotransmitter receptor localization to postsynaptic specialization membrane; postsynaptic density assembly
Cellular component: endoplasmic reticulum; extracellular region; glutamatergic synapse; synaptic cleft; transport vesicle
Genetic constraint (gnomAD): Loss-of-function variants: 11 observed, 35.01 expected, observed/expected ratio (o/e) 0.31, 90% interval 0.2 to 0.52. The upper end of that interval is the gene's LOEUF score, 0.52, which puts it in group 2 of 6, group 1 being the genes least tolerant of losing a copy. Missense variants: 435 observed, 537.05 expected, observed/expected ratio (o/e) 0.81, 90% interval 0.75 to 0.88. Synonymous variants: 262 observed, 238.88 expected, observed/expected ratio (o/e) 1.1, 90% interval 0.99 to 1.22.
Gene-disease validity (ClinGen):
ClinGen rates the evidence that NPTX1 causes each of these diseases.
autosomal dominant cerebellar ataxia (autosomal dominant): Limited. A clinically and genetically heterogeneous group of neurodegenerative diseases characterized by a slowly progressive ataxia of gait, stance and limbs, dysarthria and/or oculomotor disorder, due to cerebellar degeneration in the absence of coexisting diseases.
Homologues: Orthologues: chimpanzee NPTX1 (99% identical), macaque NPTX1 (99% identical), dog NPTX1 (96% identical), mouse Nptx1 (96% identical), rat Nptx1 (96% identical), guinea pig NPTX1 (95% identical), pig NPTX1 (84% identical), tropical clawed frog nptx1 (76% identical), zebrafish nptx1l (75% identical), rabbit NPTX1 (70% identical). Paralogues in human: NPTX2 (54% identical), PTX4 (24% identical), PTX3 (18% identical), CRP (13% identical), APCS (12% identical).
Diseases named in the same sentence as NPTX1 in open-access papers:
NPTX1 is named in the same sentence as 54 diseases in open-access papers, as found by Europe PMC text mining. Sharing a sentence is not in itself a finding about the gene and the disease. The quoted sentences say what the papers report.
lung carcinoma (10 papers, 2016 to 2025). "NPTX1 is a novel epigenetic regulation gene associated with lung cancer prognosis that enhances the level of endothelial apoptosis." (PMID 27137404, 2016). "Furthermore, NPTX1 was also identified as a novel epigenetic regulator that was associated with prognosis in lung cancer." (PMID 34440356, 2021). "Neural pentraxin-1 precursor (NPTX1) was a member of the pentraxins family and was observed down-regulated in lung cancer, colon cancer, and pancreatic cancer." (PMID 36790659, 2023). "Recently, an increasing number of studies have shown that NPTX1 is involved in the progression of various cancers, including lung cancer, colon cancer, and gastric cancer." (PMID 34646089, 2021). "In recent years, an increasing number of studies have shown that NPTX1 may be involved in the progression of cancers, including lung cancer, colon cancer, and pancreatic cancer." (PMID 31113871, 2019). "The prognostic value related to the worse prognosis of IL-8, SCG2, NCAM1, CNTN1, CADM1, NPTX1, and APOD tumor transcripts were evaluated in seven lung cancer transcriptome datasets (validation set)." (PMID 31455042, 2019).
glioma (7 papers, 2019 to 2023). A benign or malignant brain and spinal cord tumor that arises from glial cells (astrocytes, oligodendrocytes, ependymal cells). "The increased expression of NPTX1 is reported to suppress the pro-angiogenic ability of glioma cells." (PMID 36364024, 2022). "Interestingly, several long noncoding RNAs, for example, SLC26A4-AS1, upregulate NPTX1 through the NFKB1 transcription factor to produce antiangiogenic effects in glioma cells." (PMID 36364024, 2022). "Moreover, over-expression of either NPTX1 or SLC26A4-AS1 inhibited glioma cell aggressiveness and pro-angiogenic activity." (PMID 34646821, 2021). "Additionally, silencing of NFKB1 or NPTX1 resulted in restoring the pro-angiogenic and aggressive features of the glioma cells, which had been inhibited by SLC26A4-AS1 expression." (PMID 34646821, 2021). "In glioma, the level of miR-128-3p expression was dramatically attenuated in glioma clinical tissues, and miR-128-3p regulated the progression of glioma via targeting NPTX1 and activating the IRS-1/PI3K/AKT signaling pathway." (PMID 32377170, 2020). "A previous study has shown that the lncRNA SLC26A4-AS1 promotes NPTX1 transcriptional activity by recruiting NFKB1, thereby exerting antiangiogenic effects in glioma cells." (PMID 35879775, 2022). "Thus, SLC26A4-AS1 enhanced the transcriptional activity of NPTX1 via recruiting NFKB1 and hence had an anti-angiogenic effect on the glioma cells." (PMID 34646821, 2021). "SLC26A4-AS1 lncRNA has been reported to promote NPTX1 transcriptional activity by recruiting nuclear factor kappa B 1 (NF-κB 1), which has an anti-angiogenic effect on glioma cells; the problem is that SLC26A4-AS1 expression is suppressed in glioma cells." (PMID 34203727, 2021).
Cognitive impairment (6 papers, 2019 to 2025). Abnormal cognition is characterized by deficits in thinking, reasoning, or remembering. "Loss of NPTX1 led to cognitive impairments in neurodegenerative conditions." (PMID 39696694, 2024). "Interestingly, NPTX1 is a negative regulator of excitatory synapses, and its knock‐down has been shown to increase the number of excitatory synapses, while elevated levels of NPTX1 in the plasma are linked to mild cognitive impairment." (PMID 37500481, 2023). "Thus, an increase of these miRNAs would reduce the levels of NPTX1 and NPTXR and could contribute to the glutamatergic synaptic dysfunction and early cognitive impairment present in AD prior to neurodegeneration." (PMID 31092279, 2019). "Lower levels of the secreted glycoproteins NPTX1 and NPTX2 are related to more severe non-motor PD symptoms and cognitive deficits, measured by MDS-UPDRS part I, supporting previous findings in PD33,36,37." (PMID 38760408, 2024).
hepatocellular carcinoma (6 papers, 2019 to 2025). A malignant tumor that arises from hepatocytes. "Moreover, O-GlcNAc of ZNF263 at Ser 662 promotes its chromatin association with OGT and facilitates its binding to the promoters of genes such as DOCK7, NPTX1, and UFSP2, thereby influencing hepatocellular carcinoma (HCC) progression." (PMID 41280891, 2025).
pancreatic cancer (6 papers, 2015 to 2023). "Another study has reported an increase in NPTX1 expression in pancreatic cancer after treatment with metformin and aspirin." (PMID 33013829, 2020). "Previous studies have identified NPTX1 as an epigenetic target and showed that it acted as a methylation marker in human pancreatic cancer, and consistent results were also have been found in cervical cancer and colorectal cancer." (PMID 31113871, 2019). "Similarly, NPTX1 and NPTX2 can inhibit cyclin A2 and CDK2 through the Rb/E2F signaling pathway, respectively, thus inducing G0/G1 arrest in pancreatic cancer." (PMID 33013829, 2020).
Alzheimer disease (5 papers, 2021 to 2023). A progressive, neurodegenerative disease characterized by loss of function and death of nerve cells in several areas of the brain leading to loss of cognitive function such as memory and language. "Additionally, Nptx1 has been implicated in Alzheimer’s disease, where it is present in dystrophic neurites around plaques in the postmortem brain, possibly contributing to apoptosis via effects on mitochondria." (PMID 35565902, 2022). "Neuronal pentraxin 1 has been recently described as a synapse-derived plasma and CSF biomarker for Alzheimer's disease (AD)." (PMID 34054689, 2021). "Finally NPTX1, a protein involved in synaptic plasticity, was found in lower concentrations in the CSF of patients with Alzheimer’s disease, as well as in patients with symptomatic genetic frontotemporal dementia." (PMID 36482407, 2022).
colon cancer (5 papers, 2019 to 2023). "For example, the expression of NPTX1 is down-regulated in colon cancer and inhibits cell proliferation via the down-regulation of Cyclin A2 and cyclin-dependent kinase 2 (CDK2) expression." (PMID 31113871, 2019). "In another study, NPTX1 could inhibit cell proliferation through down-regulating cyclin A2 and CDK2 expression in colon cancer." (PMID 38012562, 2023). "In our study, we found that NPTX1 inhibits cell proliferation by inducing cell cycle arrest and down-regulating cycle-related proteins (Cyclin A2 and CDK2), these findings are consistent with findings in colon cancer." (PMID 31113871, 2019).
frontotemporal dementia (3 papers, 2019 to 2023). Frontotemporal dementia (FTD) comprises a group of neurodegenerative disorders, characterized by progressive changes in behavior, executive dysfunction and language impairment, as a result of degeneration of the medial prefrontal and frontoinsular cortices. "Several biomarker discovery studies using mass spectrometry methods have identified changes in CSF levels of NPTX2 or NPTX1 in AD and decreased Neuronal Pentraxin Receptor in Frontotemporal Dementia." (PMID 31853477, 2019).
dementia (2 papers, 2022 to 2024). Loss of intellectual abilities interfering with an individual's social and occupational functions. "Furthermore, we could also speculate on an increase of CSF NPTX1 levels in the earliest stages of the disease, followed by a drop in the dementia phase." (PMID 34460014, 2022). "There was a significant interaction with group for SYT1, NPTX1, NPTX2, and NPTX-R; slopes of AD dementia patients (st.B[SE] –0.15[0.05], –0.11[0.04], –0.13 [0.04], and –0.10[0.04] respectively) differed from those of SCD/MCI-A– subjects." (PMID 39121126, 2024). "Overall, these results reflect an increase of NPTX1 and NPTXR in pre-symptomatic stages of genetic AD, MCI and early stages of AD, whereas they decrease in later dementia stages." (PMID 34460014, 2022). "In addition, the behaviour of NPTX1 and NPTXR could be explained by the biphasic activity of the glutamatergic system in the hippocampus, with increased activity in MCI, followed by a decline during the dementia stage." (PMID 34460014, 2022).
amnesia (1 paper, 2025). Pathologic partial or complete loss of the ability to recall past experiences ( AMNESIA, RETROGRADE) or to form new memories ( AMNESIA, ANTEROGRADE). "That is to say, during aging, Nptx2 downregulation-induced disruption of local perisomatic inhibition in DG engram precedes Nptx1 downregulation-induced disruption of long-range MEC-DG excitatory projection; this probably explains why generalization always emerges before amnesia in aged individuals." (PMID 40750687, 2025).
Anxiety (1 paper, 2023). Intense feelings of nervousness, tension, or panic often arise in response to interpersonal stresses. "Some members of the pentraxin gene family that we found to be modulated here (Nptxr|Nptx1|Nptx2) are involved in anxiety and responses to stress, which support their modulation in stressed animals." (PMID 36890154, 2023).
brain cancer (1 paper, 2020). A primary or metastatic malignant neoplasm affecting the brain. "Given the fact that NPTX1 has been implicated in neurodegeneration, brain cancers and in compromised blood-brain barrier, further investigation of NPTX1 may be of interest especially since air pollution exposure is also linked to neurodegeneration and blood brain barrier dysfunction." (PMID 32487172, 2020).
Cachexia (1 paper, 2019). Severe weight loss, wasting of muscle, loss of appetite, and general debility related to a chronic disease. "Based on the fact that circulating levels of tumor-derived factors were correlated with cachexia development and predicted outcome in cancer, we also investigated the predictive potential of seven transcripts (NCAM1, CNTN1, SCG2, CADM1, IL-8, NPTX1, and APOD)." (PMID 31455042, 2019).
chordoma (1 paper, 2023). Chordomas are rare malignant tumors arising from embryonic remnants of the notochord in axial skeleton. "The expression of AMOT, RYR3, P2RX5, and TNFSF14 were higher in recurrent chordomas than primary chordomas while NPTX1 was contrast." (PMID 38012562, 2023). "Then, we performed the luciferase reporter assay to confirm that miR- 186-5p could directly bind to the 3′-UTR of AMOT and miR- 125b-5p to NPTX1 in U-CH1 chordoma cells." (PMID 38012562, 2023). "miR-186-5p, miR-125b-5p, miR-1260a, and their target protein mRNAs including AMOT, NPTX1, RYR3, P2RX5, TNFSF14 may be the basement of chordoma research." (PMID 38012562, 2023).
gastrointestinal stromal tumor (1 paper, 2020). "NPTX1 and NPTX2 were reported to cause dysfunction of the PI3K/AKT/mTOR pathway thereby affecting tumor progression in glioma, gastrointestinal stromal tumors (GIST) and subependymal giant cell astrocytoma." (PMID 33013829, 2020).
gynecologic cancers (1 paper, 2025). "Together with proteomic evidence showing that both proteins localize to membrane-associated structures involved in motility and structural remodeling, these findings provide biological plausibility for our hypothesis that FAM171A2 and NPTX1 may converge on similar pathways in gynecologic cancers." (PMID 41303609, 2025).
Hernia (1 paper, 2009). "These genes may be involved in the estrogen receptor signaling pathway (KIF18A and NPTX1), the epithelial-mesenchymal transition (ELF5) and the collagen metabolism pathway (COL23A1), which are associated with the important molecular characteristics of hernia pathophysiology." (PMID 19287495, 2009).
ischemia (1 paper, 2017). A hypoperfusion of the BLOOD through an organ or tissue caused by a PATHOLOGIC CONSTRICTION or obstruction of its BLOOD VESSELS, or an absence of BLOOD CIRCULATION. "Some of these regulators have been already associated with different forms of ischemia (e.g. Creb, Stat1, Bcl6, miR-122, miR-21, miR-214, miR-493) while others have not (e.g. Maf, Nptx1, Lef1, miR-290, miR-297, miR-466)." (PMID 29121052, 2017).
kidney failure (1 paper, 2022). An acute or chronic condition that is characterized by the inability of the kidneys to adequately filter the blood. "Furthermore, Nptx1 is upregulated in the aorta of uremic mice, suggesting that the induction by IS and IAA observed in vitro in endothelial cells may occur in vivo during kidney failure." (PMID 35216489, 2022).
melanoma (1 paper, 2023). A malignant, usually aggressive tumor composed of atypical, neoplastic melanocytes. "Then, the impact of circRPS5, miR-151a and NPTX1 expression on the progression of melanoma cell were determined by gain- and loss-of-function assays." (PMID 37384727, 2023). "Subsequently, we found that circRPS5 was negatively associated with melanoma progression by sponging miR-151a to influence the expression of neuronal pentraxin 1 (NPTX1)." (PMID 37384727, 2023). "Whereas, knockdown of NPTX1 inhibited cell apoptosis in melanoma cells, these effects were largely abolished by circRPS5 overexpression." (PMID 37384727, 2023). "Conversely, the increased EdU positive cells after NPTX1 knockdown in melanoma cells were largely reversed by circRPS5 overexpression." (PMID 37384727, 2023). "Taken together, these data support that circRPS5 as a ceRNA to promote NPTX1-mediated proliferation and metastasis in melanoma by sponging miR-151a." (PMID 37384727, 2023). "qRT-PCR and western blotting results indicated that miR-151a mimics significantly decreased NPTX1 expression, whereas miR-151a inhibitors markedly enhanced NPTX1 expression in melanoma cells." (PMID 37384727, 2023). "Altogether, these data suggested that circRPS5 suppressed the progression of melanoma cells by upregulating the expression of NPTX1." (PMID 37384727, 2023). "Compared with the HeMa-Lp cells, only NPTX1 expression was down-regulated in the both melanoma cells." (PMID 37384727, 2023). "Overexpression of CircRPS5 can inhibit the proliferation, migration and invasion of melanoma cells via the miR-151a/NPTX1 pathway." (PMID 37384727, 2023). "The invasion and migration of melanoma cells were also promoted by NPTX1 knockdown; however, circRPS5 overexpression hindered these influences." (PMID 37384727, 2023). "CCK-8 and colony formation assays in melanoma cells showed that overexpression of NPTX1 led to inhibition of the proliferation capabilities, but this effect could be partly attenuated by circRPS5 knockdown." (PMID 37384727, 2023). "Moreover, the expression of NPTX1 was detected after circRPS5 overexpression and knockdown in melanoma cells, respectively." (PMID 37384727, 2023). "Additionally, NPTX1 was found to induce cell apoptosis in melanoma cells, which was restored after circRPS5 knockdown." (PMID 37384727, 2023). "To further confirm whether circRPS5 plays an inhibitory role in OS by up-regulating NPTX1 expression, we transfected NC, pc-NPTX1, sh- NPTX1, pc-NPTX1 + sh-circRPS5, and sh-NPTX1 + lv-circRPS5 into melanoma cells." (PMID 37384727, 2023). "Mechanistically, circRPS5 could rescue the expression of NPTX1 by sponging miR-151a, thereby inhibiting melanoma progression." (PMID 37384727, 2023). "In addition, NPTX1 knockdown significantly reversed the circRPS5 overexpression induced promotion of proliferation, invasion and migration of melanoma cells." (PMID 37384727, 2023). "Importantly, the expression of NPTX1 is negatively regulated by circRPS5 in melanoma cells." (PMID 37384727, 2023). "Furthermore, transwell assay revealed that NPTX1 overexpression obviously impeded melanoma cells invasion and migration, and this effect could be partly attenuated by circRPS5 knockdown." (PMID 37384727, 2023). "Recently, NPTX1 has been found to have decreased expression in diverse cancers, but its expression and impact in melanoma has not been defined yet." (PMID 37384727, 2023). "Among them, 6 genes (NPTX1, AUTS2, RPS6KA2, KAT2B, MYO5A and HMG20B) were simultaneously downregulated in the melanoma samples compared with the noncancerous samples in GSE31909 and GSE35388 microarray data." (PMID 37384727, 2023).
thymoma (1 paper, 2021). A neoplasm arising from the epithelial cells of the thymus. "Furthermore, the diagnostic value of NPTX1 in thymoma by receiver operating characteristic curve (ROC) was analyzed." (PMID 33478183, 2021). "NPTX1 was highly expressed in thymoma patients, and had diagnostic value for thymoma." (PMID 33478183, 2021). "By mRNA microarray analysis of 31 thymomas and peritumoral thymic tissues, we found that the transcription level of neuronal pentraxin 1 (NPTX1) gene was up-regulated more than 4 times in thymomas." (PMID 33478183, 2021).
uremia (1 paper, 2022). A clinical syndrome associated with the retention of renal waste products or uremic toxins in the blood. "The adenine mouse model of CKD was used to analyze NPTX1 expression in the burden of uremia." (PMID 35216489, 2022).
viral infection (1 paper, 2024). "Specifically, the identification of autoantibodies targeting proteins such as NPTX1, amyloid, neuron lysate, and MOBP suggests that these proteins may play a role in the pathogenesis of HSCR through molecular mimicry mechanisms initiated by viral infection." (PMID 39493374, 2024).